STAT3 (signal transducer and activator of transcription 3)
Diseases named in the same sentence as STAT3 in open-access papers (continued):
Sharing a sentence is not in itself a finding about the gene and the disease.
renal fibrosis (118 papers, 2012 to 2025). A final common manifestation of a wide variety of chronic kidney diseases characterized by glomerulosclerosis and tubulointerstitial fibrosis. "Smad3 is a key downstream factor of TGFβ1, and STAT3 acts downstream of many membrane receptors associated with renal fibrosis, including TGF βreceptors." (PMID 41275091, 2025). "The in-vivo results verified that the therapeutic effect of hirudin on renal fibrosis was probably linked to the inhibition of ferroptosis via the STAT3/NLRP3 signaling pathway." (PMID 40298655, 2025). "STAT3 is also associated with the progression of renal fibrosis, and the induction of STAT3 acetylation can promote renal fibrosis." (PMID 40298655, 2025). "Numerous studies have shown that multiple signaling pathways (including PI3K/AKT, STAT3 Notch, Wnt/beta-catenin, and Hedgehog) are associated with renal fibrosis fibers." (PMID 36733505, 2023). "Other reports indicated that MSCs can protect against renal fibrosis caused by obstruction via downregulating STAT3 and upregulating STAT3-dependent MMP-9." (PMID 36422526, 2022). "The diabetic transgenic rats showed advancement in the pathological features such a renal tubular damage, collagen accumulation and enhancement in STAT3 associated mechanism of renal fibrosis." (PMID 34233296, 2021). "Fyn deficiency is associated with attenuation of renal fibrosis through inhibition of p-Stat3 (Tyr 705)." (PMID 32565740, 2020). "In conclusion, in vivo, our findings show a critical role for the inhibitory effect of PrdxV in EGFR/Stat3 activation associated with the development of renal fibrosis after UUO." (PMID 31217524, 2019). "Activation of the epidermal growth factor receptor (EGFR)/signal transducer and activator of transcription 3 (Stat3) signaling pathway has been reported to be associated with renal fibrosis." (PMID 31217524, 2019). "The persistent and prominent increase of p-STAT3 implicated a important role of this protein in progression of renal fibrosis after UUO and interstitial fibroblasts activation." (PMID 31492196, 2019). "The anti-fibrotic effect of rhein involves suppression of the STAT3 signaling pathway, which is associated with apoptosis of tubular cell and renal fibrosis." (PMID 31492196, 2019). "The decrease in phosphorylated extracellular signal-regulated kinase (p-ERK) and phosphorylated signal transducer and activator of transcription 3 (p-STAT3) was suggested as a major underlying mechanism responsible for the effect of dulaglutide in renal fibrosis." (PMID 41244507, 2025). "Activated STAT3 was a key factor in the development of renal fibrosis caused by hyperuricemia." (PMID 37954274, 2023). "Moreover, Il-6 can trigger TECs to generate collagen and accelerate interstitial fibrosis, which is also associated with enhanced STAT3 activation 11; while blocking Il-6 protects against IR-induced renal fibrosis by suppressing STAT3 activation." (PMID 35664078, 2022). "Our results revealed that the elevated expression of fibronectin and α-SMA induced by ectopic expression of miR-155-5p in NRK-49F cells was effectively eliminated by loss function of STAT3, suggesting that miR-155-5p is involved in renal fibrosis via regulating the phosphorylation of STAT3." (PMID 32587662, 2020). "In a model of renal fibrosis, activation of STAT3 was associated with the up-regulation of MMP-9." (PMID 31557909, 2019). "After renal mass ablation, several intracellular molecules associated with renal fibrosis, including NF-kappaB p65, Smad-3, signal transducer and activator of transcription-3 and extracellular regulated kinase 1/2, are phosphorylated; suramin treatment inhibited their phosphorylation." (PMID 22558380, 2012). "Therefore, whether folate deficiency might enhance renal fibrosis via activation of STAT3 and Smad2/3 signaling is worthy of investigation." (PMID 37630806, 2023).
renal fibrosis (continued). "Moreover, silencing of HDAC1 or HDAC2 blocked renal fibroblast proliferation by reducing phosphorylation of STAT3 (signal transducer and activator of transcription 3), a signaling molecule associated with the proliferation of renal fibroblasts and the development of renal fibrosis." (PMID 33398599, 2021). "Furthermore, renal fibrosis induced by miR-155-5p overexpression is blocked by STAT3 deficiency." (PMID 32587662, 2020). "Moreover, silencing of HDAC1 or HDAC2 using specific siRNA blocked renal fibroblast proliferation and reduced phosphorylation of STAT3 (signal transducer and activator of transcription 3), a signaling molecule associated with proliferation of renal fibroblasts and development of renal fibrosis." (PMID 25972812, 2015). "For example, STAT3 is a transcription factor that plays a role in many physiological processes, including the kidney's response to injury and the progression of certain renal diseases (e.g., diabetic nephropathy, renal fibrosis, and HIV-associated nephropathy)." (PMID 23637735, 2013). "Luteolin inhibited the anti‐inflammatory response and OS by suppressing the activity of the signal transducer and activator of transcription 3 (STAT3) pathway, thereby reducing renal fibrosis and delaying the progression of DKD." (PMID 41019174, 2025). "Increasing the activity of phosphorylated STAT3 or STAT3 can promote the proliferation of renal interstitial fibroblasts and advancement of renal fibrosis." (PMID 40468401, 2025). "The positive correlation between Hcy and phosphorylated STAT3 ratio, as well as TGF-β1 and phosphorylated Smad2/3 ratio in renal fibrosis tissues, revealed the mechanisms of folate deficiency effects." (PMID 39919369, 2025). "To elucidate the underlying mechanism by which HDAC11 induces EMT and renal fibrosis in the UUO model, we investigated the effect of HDAC11 inhibition on the phosphorylation of Smad3 (p-Smad3) and STAT3 (p-STAT3) in the kidney and cultured RTPCs." (PMID 40386380, 2025). "This study demonstrated that hirudin effectively treats renal fibrosis by regulating ferroptosis through the STAT3/NLRP3 signaling pathway." (PMID 40298655, 2025). "Chronic treatment with silymarin nanoliposomes effectively ameliorated inflammation, OS, and renal fibrosis via inhibiting JAK2/STAT3/suppressor of cytokine signaling 1 and TGF‐β/Smad signaling pathways in diabetic rats with STZ‐induced kidney injury." (PMID 41019174, 2025). "Due to the involvement of the IL-6/STAT3 pathway in renal fibrosis, the blockade of STAT3 phosphorylation is a promising therapeutic approach in the UUO model in vivo." (PMID 39684261, 2024). "With reference to the report that miR199a‐3p repressed SOCS7 expression resulting in STAT3 activation during human renal fibrosis, the luciferase reporter assays in the present study confirmed that miR‐199a‐3p directly binds to SOCS7." (PMID 39431622, 2024). "The inhibition of STAT3 can attenuate the progression of renal fibrosis and reduce the production of macrophages and inflammatory cytokines." (PMID 37635867, 2023). "The inhibition of STAT3 ameliorated kidney function and alleviated renal fibrosis in the hyperuricemic nephropathy mice." (PMID 37954274, 2023). "Based on these studies, PRMT is a key regulator in the TGF‐β1/Smad3 signaling pathway and STAT3 signaling and functions in renal fibrosis." (PMID 37525933, 2023). "The genetic overexpression of TGF-β in mice induces renal fibrosis through the upregulation of Egr1, STAT3, and AP-1." (PMID 37373116, 2023). "This study proved that the inhibition of mTOR and STAT3 expression has a therapeutic effect on preventing renal fibrosis." (PMID 35164031, 2022). "In our present study, we found that RAGE was induced by TGF-β1 and UUO, and then mediated autophagy to increase the renal fibrosis via STAT3/Atg7 axis in vitro and vivo." (PMID 35461309, 2022).
renal fibrosis (continued). "Meanwhile, we elucidated a novel cross-regulation between MyD88 and STAT3 or Smad3, thus reaffirming the plausibility of MyD88 as a potential therapeutic target for renal fibrosis." (PMID 35628363, 2022). "Collectively, rhein protects rats from renal fibrosis by regulating SirT1/STAT3/Twist1 pathway to promote Cpt1a-mediated fatty acid degradation." (PMID 35408745, 2022). "The aim of this study was to investigate the beneficial effect of mTOR/STAT3 ODN via the regulation of autophagy appearance on unilateral ureteral obstruction (UUO)-induced renal fibrosis." (PMID 35164031, 2022). "In mouse kidneys with fibrosis and inflammatory infiltration, sample sequencing to a depth of 30 million reads and network analysis showed that the top TFs, such as Irf1, Nfkb1, and Stat3, are important drivers of renal fibrosis progression." (PMID 36246123, 2022). "In this study, we demonstrated that rhein prevents renal fibrosis by promoting Cpt1a-mediated FAO through SirT1/STAT3/Twist1 pathway." (PMID 35408745, 2022). "Fyn aggravates renal fibrosis by promoting STAT3 phosphorylation, which indicates that Fyn can promote renal inflammation and fibrosis in the middle stage." (PMID 35883540, 2022). "This process is mediated by oxidative stress and STAT3 cellular signaling pathways involved in renal fibrosis." (PMID 36139886, 2022). "To study SSLF's functional mechanism and understand its potential inhibitory role in renal fibrosis, first, we found that STAT3, VEGFA, and AKT1 of the intersection genes of SSLF and RIF are the core proteins in the intersection genes." (PMID 35399631, 2022). "This study evaluated how the change in autophagy appearance by the inhibition of mTOR/STAT3 function affects renal fibrosis after injury." (PMID 35164031, 2022). "Mechanistically, RAGE mediated the TGF-β1-triggered Stat3 activation and then promoted autophagy to increase renal fibrosis via upregulation of Atg7." (PMID 35461309, 2022). "Renal fibrosis and apoptosis are inhibited by the regulation of autophagy after the suppression of mTOR and STAT3 expression." (PMID 35164031, 2022). "Here, we present that rhein upregulated Cpt1a-mediated FAO through the SirT1/STAT3/Twist1 pathway to improve renal fibrosis." (PMID 35408745, 2022). "Toward these ends, it investigates the inhibitory effects of mTOR/STAT3 decoy ODN on preventing renal fibrosis." (PMID 35164031, 2022). "Collectively, RAGE in proximal tubular cells promotes the autophagy to increase renal fibrosis via upregulation of Stat3/Atg7 axis." (PMID 35461309, 2022). "Mechanistically, RAGE mediated TGF-β1-induced phosphorylation of Stat3 and directly upregulated the Atg7 to increase the level of autophagy, and ultimately resulting in renal fibrosis." (PMID 35461309, 2022). "Suppressing STAT3 activation protects against IR-induced renal fibrosis 12, and ameliorates renal interstitial fibrosis in diabetic mice." (PMID 35664078, 2022). "Mechanistically, TGF-β1 stimulated the RAGE and then activated STAT3 to increase autophagy via directly upregulation of Atg7, and then promoted the progression of renal fibrosis." (PMID 35461309, 2022). "Meanwhile, several studies have shown that increased STAT3 activation is involved in UUO-induced renal fibrosis." (PMID 35628363, 2022). "The results of this research confirm autophagy regulation via STAT3 decoy ODNs in a UUO-induced renal fibrosis model." (PMID 33806080, 2021). "Taken together, these data suggest that the suppression of STAT3 transcription factors can modulate autophagy in UUO-induced renal fibrosis." (PMID 33806080, 2021). "Experimental evidence found from a murine kidney injury model using unilateral ureteral obstruction links STAT3 with amplified deposition of extracellular matrix proteins, thereby driving the development of renal fibrosis." (PMID 34233296, 2021).
renal fibrosis (continued). "Our present results show that the proteins involved in the STAT3 mediated renal fibrosis mechanism are highly elevated in the DM TG rats with cardiac specific IGF-IIRα overexpression." (PMID 34233296, 2021). "In the present study, on the 14th day after obstruction, the mRNA levels of α-SMA, JAK2 and STAT3 were significantly increased with increased renal fibrosis degree." (PMID 33407391, 2021). "Previous studies have demonstrated that STAT3 exerts anti-fibrotic effects in many fibrosis diseases, such as systemic sclerosis (SSc), skin fibrosis, and renal fibrosis." (PMID 33804639, 2021). "Immunohistochemical staining was performed to investigate the regulatory effects of STAT3 transcription factors in UUO-induced renal fibrosis." (PMID 33806080, 2021). "The signal transducer and activator of transcription 3 (STAT3) is activated as a potential transcription factor, which mediates the stimulation of renal fibrosis." (PMID 33806080, 2021). "The results of animal model studies showed that STAT3 mediated renal fibrosis by inhibiting leukocyte infiltration and proinflammatory cytokine expression and the activation of renal interstitial fibrosis." (PMID 34112221, 2021). "Dasatinib and nifuroxazide mitigated UUO induced-renal fibrosis through inhibiting Src/STAT-3/NF-κB signaling." (PMID 34199002, 2021). "In certain tissues, increased STAT3 activity mediates activation of renal interstitial fibroblasts and the progression of renal fibrosis." (PMID 34054555, 2021). "We use losartan, an ARB can significantly attenuate renal fibrosis and renal tubular cell apoptosis by inhibiting phosphorylation of the signaling protein STAT3 in a rat model of UUO, as a positive control drug." (PMID 33407391, 2021). "Among the downstream pathways of TGF-β, the activation of STAT3 has been found to play a role in renal fibrosis." (PMID 33407391, 2021). "All the previous evidence indicates that STAT3 plays a critical role in the pathogenesis of renal fibrosis." (PMID 32587662, 2020). "In mechanism, our data demonstrate that miR-155-5p promotes renal fibrosis by increasing the phosphorylated activation of STAT3 via targeting SOCS1/6." (PMID 32587662, 2020). "Previous study showed that STAT3 inhibitor, S3I-301, reduced renal fibrosis in a mouse unilateral ureteral obstruction model." (PMID 32071300, 2020). "Consistent with other studies, we observed a significant increase in the STAT3 activation in renal fibrosis, and miR-155-5p is capable of activating STAT3 both in vitro and in vivo." (PMID 32587662, 2020). "Further, the impact of rhein on STAT3 phosphorylation, a critical component in the apoptosis of tubular cell as well as progression of renal fibrosis, was examined." (PMID 31492196, 2019). "Prior investigations have demonstrated that activities of the STAT3 signaling contribute to the progression of renal fibrosis in the UUO model." (PMID 31492196, 2019). "In vivo experiments suggested the activation of site-specific EGFR (Tyr1068) and subsequent activation of Stat3 as a mechanism for progressive renal fibrosis in UUO-induced PrdxVsi mice." (PMID 31217524, 2019). "This has been demonstrated for Fyn, a member of the Src family kinases that promotes renal fibrosis in adult mice with UUO involving STAT3 signaling." (PMID 31846485, 2019). "Activation of Stat3 induces the expression of multiple genes that results in the progression of renal fibrosis." (PMID 31217524, 2019). "We observed that renal fibrosis induced by UUO was more severe in PrdxVsi mice than in PrdxVwt mice and that this effect was associated with increased EGFR/Stat3 signaling pathway activity." (PMID 31217524, 2019). "The results also undoubtedly showed that treatment with rhein partly inhibited the UUO induced STAT3 phosphorylation as well as renal fibrosis." (PMID 31492196, 2019). "Elsewhere, the selective inhibitor STAT3 attenuated renal fibrosis by inactivating interstitial fibroblasts in vivo." (PMID 30177595, 2018).
renal fibrosis (continued). "One of the products of EPC is leukemia inhibitory factor, which itself activated the STAT3 pathway and mitigated formation of myofibroblasts, whereas a more potent gp130/STAT3 agonist, a fusion protein hyper‐IL‐6, also prevented renal fibrosis." (PMID 28297566, 2017). "Our recent studies have shown that activation of EGFR mediates the development of renal fibrosis and peritoneal fibrosis and that STAT3 acts downstream of EGFR." (PMID 29179471, 2017). "The protective effect on renal fibrosis was correlated with dephosphorylation of the signal transducer and activator of transcription 3 (STAT3) pathway." (PMID 25954204, 2015). "Activation of STAT3 is associated with many forms of renal injury and the JAK2/STAT3 pathway has been implicated in the progression of renal fibrosis in several models of renal disease." (PMID 24167575, 2013). "p-STAT3 and NLRP3 levels were associated with the activation or inhibition of ferroptosis, suggesting that the effect of hirudin on renal fibrosis by inhibiting ferroptosis may be related to the STAT3/NLRP3 signaling pathway." (PMID 40298655, 2025). "Based on these findings, we hypothesized that hirudin might ameliorate renal fibrosis by alleviating ferroptosis, and that this therapeutic effect could be mediated through the STAT3/NLRP3 signaling pathway." (PMID 40298655, 2025). "Similarly, the combination of Astragalus membranaceus and Panax notoginseng synergistically alleviates renal fibrosis via the HIF-1α/JAK2/STAT3 axis." (PMID 41487503, 2025). "Hirudin improved renal fibrosis by inhibiting ferroptosis via the STAT3/NLRP3 signaling pathway." (PMID 40298655, 2025). "The inhibition of STAT3 in diabetic nephropathy can improve renal fibrosis and inflammation." (PMID 40298655, 2025). "Additionally, CXCL6 can accelerate the development of renal fibrosis through the JAK/STAT3 signaling pathway." (PMID 38168591, 2024). "And promotes renal fibrosis by regulating inflammatory signaling pathways such as JAK2/STAT3." (PMID 39705287, 2024). "Inhibition of STAT3 in renal tubular epithelial cells prevents renal fibrosis." (PMID 36747131, 2023). "Inhibition of STAT3 in tubular epithelial cells prevented renal fibrosis in diabetic mice." (PMID 37630806, 2023). "Blockade of IL‐6 trans‐signaling prevents renal fibrosis by suppressing STAT3 activation." (PMID 37525933, 2023). "Smad3 acetylation and STAT3 acetylation are involved in the development of renal fibrosis." (PMID 37635867, 2023). "Notably, several studies have shown that increased STAT3 activation is involved in UUO-induced renal fibrosis in mesenchymal fibroblasts." (PMID 35628363, 2022). "Additionally, nintedanib suppressed PDGFRβ, FGFR1, FGFR2, and VEGFR2 phosphorylation and blocked the expressions of STAT3, NF-κB, and Smad3 to diminish macrophage infiltration, thereby ultimately exerting anti-renal fibrosis effects." (PMID 35250597, 2022). "Previous studies have shown that signaling factors such as JAK2/STAT3, Smad3, and Myd88 play a regulatory role in renal fibrosis, and β-elemene is a plant-derived sesquiterpenoid organic compound that has been shown to have anti-inflammatory, anti-cancer, and immunomodulatory effects." (PMID 35628363, 2022). "In this study, we found that β-elemene attenuated renal interstitial fibrosis and down-regulated ECM protein expression in UUO mice by inhibiting STAT3 and Smad3 signaling via suppressing MyD88 expression, suggesting that β-elemene is effective in the treatment of renal fibrosis." (PMID 35628363, 2022). "Due to its direct correlation with renal fibrosis, STAT3 is a critical element in inflammation." (PMID 36139886, 2022).